MMP9 (matrix metallopeptidase 9)
Diseases named in the same sentence as MMP9 in open-access papers (continued):
Sharing a sentence is not in itself a finding about the gene and the disease.
tumor (continued). "Regarding MMP-9, we and others, have shown that increased MMP-9 activity leads to tumor regression." (PMID 29387062, 2017). "Indeed, the numbers of MMP9+ Ly6G+cells and S100A8+ Ly6G+ cells in the primary tumor and in the lung were significantly decreased by WCE treatment." (PMID 29142311, 2017). "Mangiferin considerably decreased tumor proliferation, weight, and volume, and enhanced apoptosis, as well as also decreased the expression levels of MMP-7, MMP-9, active β-catenin, vimentin, while increasing the expression of E-cadherin in in vitro MDA-MB-231 xenograft mice." (PMID 28464819, 2017). "Likewise, numerous studies show many of these signaling pathways are blocked by apigenin in tumor models in particular NF-kB signaling which controls the downstream release of TGF-b and activity of MMP-9, themselves involved with TAM/TANs and Treg recruitment." (PMID 28441391, 2017). "Mechanistically, this could be explained by stabilizing gelatinase B (MMP-9), thereby allowing enhanced degradation of the extracellular matrix and tumor cell dissemination." (PMID 28804221, 2017). "In obese tumor patients treated with amiloride, increased MMP3 protein levels and MMP9 activities were detected in tumor tissues, suggesting that exosome-mediated MMP3 protein transfer and subsequent MMP9 activation may also occur in the human body." (PMID 29137230, 2017). "ADP (via PI3K/Akt signaling) inhibits cell migration and invasion by blocking PI3K activity, reducing p-Akt levels, and downregulating MMP-9 expression in tumor cells (data not shown)." (PMID 28415709, 2017). "In addition to its direct effects on cell proliferation, NF-κB can alter tumor growth and progression through activation of its target genes, including IL-6, VEGF, MMP9 and TNF- α." (PMID 28978058, 2017). "In addition, MMPs has been reported to play crucial roles in invasion and metastasis of tumor cells, thus protein levels of two of most important MMPs, MMP-2 and MMP-9, in LL/2-R and LL/2-P cells and tumors were measured by western blotting assay." (PMID 28978115, 2017). "Western blotting and immunohistochemical assays revealed the upregulation of invasion-related proteins MMP2 and MMP9, and proliferation-related protein Cyclin D1 in the CEP55-overexpressing tumour tissues, which coincided with the aggressive phenotype displayed by Capan-1/CEP55 cells." (PMID 28724890, 2017). "After the LH treatment, the expression of MMP-9 was obviously suppressed in primary tumor, while no positive expression of was found in the tissue of lymph nodes and lungs without metastatic tumor cells." (PMID 27906672, 2017). "Whether tumor and fibroblast cells in the breast TME cooperate in the regulation of MMP9-driven tumor vasculature is currently unknown." (PMID 28423685, 2017). "Immunostaining detected rPH-positive cells only in tumor-fibroblast xenografts and depletion of MMP9 did not affect the presence of rat fibroblasts in the xenografts." (PMID 28423685, 2017). "S100A4 secreted by tumor and stromal cells can stimulate angiogenesis by synergizing with VEGF to promote endothelial cell migration through the increase in RAGE-induced KDR and MMP-9 expression in a melanoma animal xenograft-model." (PMID 29069865, 2017). "In addition, the suppressive effect of SIS3 on cancer progression was also associated with inhibition of angiogenesis (CD31 and VEGF) and tumour-invasive and metastatic activities, including the expression of MMP-2, MMP-9, MMP-13 and CXCR4." (PMID 28262747, 2017). "In addition, several studies have reported that the secretion or expression of MMPs by tumor cells (including the secreted MMP-2, MMP-9 and the membrane type MMP-14) can lead to the shedding of MICA/B at their surface." (PMID 28423623, 2017). "As demonstrated in in vitro studies, both MMP-9 and NGAL led to the increase in tumor sizes." (PMID 29089666, 2017).
tumor (continued). "Univariate analysis indicates that TNM stage, adjuvant chemotherapy, Rab1B and MMP9 proteins are significant predictors for OS and PFS of CRC patients (All P < 0.05), and Tumor depth is a marginally significant predictor for OS and PFS (P =0.065 and P =0.059, respectively)." (PMID 28316326, 2017). "Simultaneously, high levels of miR-146a-5p also raise EMMPRIN expression in the same tumor cell, thus inducing angiogenesis by enhancing VEGF and MMP-9 secretion and by directly affecting endothelial cells, as observed in the in vitro tube formation and wound assays and suggested before." (PMID 29354134, 2017). "In terms of MMP-9 and MMP-2, both were not up-regulated by sorafenib and IFN-α, and other factors associated with tumor invasion and migration require further confirmation in our future research." (PMID 29100435, 2017). "The increase in MMP-9 expression was not seen in the tumor cells, but only in the stromal compartment." (PMID 28819116, 2017). "Most importantly, a more recent study has shown that one of the major, exceptionally potent, and critical tumor angiogenesis-inducing factors, MMP-9, is derived from neutrophils and not the previously thought M2 macrophages." (PMID 28149530, 2017). "In a preclinical tumor model, ADT also enhances the expression of macrophage-recruiting chemokine CSF1 and M2-promoting cytokines, such as IL13 and IL10 in PCa cells, resulting in more macrophage infiltration and expression of MMP9 and VEGF46." (PMID 29142311, 2017). "When equal amounts of lung tumor tissue lysates were loaded for the gelatin zymography test, we detected increased MMP9 activities in lung tumor tissues from obese tumor patients compared with non-obese tumor patients." (PMID 29137230, 2017). "This chemokine is also associated with an inflammatory response by recruiting leukocytes into the tumor stroma, where they contribute to angiogenesis by producing angiogenic factors, by remodeling the ECM via stimulated secretion of MMP-9, and by direct differentiation into ECs." (PMID 29112161, 2017). "Furthermore, genes reported to promote tumor metastasis in various cancers, including SRC, TGFB1 and MMP9, were upregulated by CTCF." (PMID 28977939, 2017). "It has been shown that Ku80 could upregulate metalloproteinase (MMP)-2 and MMP-9 expression through activating ERK/JNK pathway, where MMPs correlate to angiogenesis, oncogenesis, tumor invasion and metastasis." (PMID 28399858, 2017). "Furthermore, we stained the intracranial tumours with IKBKE, YAP1, MMP-2, MMP-9, E-cadherin, N-cadherin, β-catenin, vimentin, and snail." (PMID 28548934, 2017). "The high expression of Galectin-1 in PDAC, along with its positive relation with the expression of EMT markers and MMP9 expression, prompted us to investigate whether PSC-derived Galectin-1 functions as a tumor promoter." (PMID 29156810, 2017). "Furthermore, systemic treatment of SIS3 also significantly altered the tumour-friendly microenvironment, including suppression on angiogenesis (VEGF expression and CD31+ vessels) and tumour-invasive factors (MMP-2, MMP-9, MMP-13 and CXCR4)." (PMID 28262747, 2017). "Furthermore, co-treatment of tumor cells with TGF-β and TNF/IL-1β cytokines cooperatively stimulated expression of MMP9." (PMID 28423685, 2017). "Moreover, the subsequent mechanism investigation suggested that CAPN2 promoted tumor progression by activating AKT/mTOR signaling, enhancing epithelial mesenchymal transition (EMT) and MMP9 levels." (PMID 29228653, 2017). "To address the role of tumor-derived MMP9 in tumor vascularization, we utilized MDA-MB-231 cells expressing constitutively-active ALK5/TGFBR1-T204D (caALK5) and MDA-MB-231-caALK5 cells depleted of MMP9 by shRNA." (PMID 28423685, 2017).
tumor (continued). "Indeed, estrogen induces neutrophil expression of a plethora of genes encoding protumoral cytokines/chemokines(e.g. CXCL1, CXCL2, S100A8, S100A9), matrix metalloproteinases(MMP3, MMP9) and COX-2 that are all known to promote tumor growth and metastasis." (PMID 28429725, 2017). "Because Notch signaling is thought to be related to MMP-9 activation, TNC or TNIIIA2 might activate Notch signals through the production of MMP and participate in tumor invasion." (PMID 28106752, 2017). "Coculture of the M1 with Hepa1-6 cells showed a remarkable inhibition of migration and invasion of the tumor cells and decreased expressions of matrix metalloproteinase (MMP)-9 and MMP-2 without notable apoptosis of Hepa1-6 cells." (PMID 28243242, 2017). "TANs recruited by tumor then release pro-growth and pro-invasion factors including hepatocyte growth factor (HGF), reactive oxygen species (ROS), reactive nitrogen species (RNS), neutrophil elastase (NE), neutrophil collagenase (MMP8), and gelatinase B (MMP9)." (PMID 28223716, 2017). "We found that 3T3-A-EXO promotes 3LL tumor cell invasion in vitro through increasing MMP9 activity but not protein levels." (PMID 29137230, 2017). "Tumor cells themselves or infiltrated immune cells of the tumor stroma, especially TAMs, either directly provide a conducive environment for lymphangiogenesis or indirectly generate prolymphangiogenic factors like VEGF-C, VEGF-D, and MMP9." (PMID 28804221, 2017). "We were puzzled by the strong impact of p38 inactivation on tumor vasculature even though MMP9 was not affected." (PMID 28977919, 2017). "N1 neutrophils are anti-tumoral and are characterized by hypersegmented nuclei, increased expression of TNF-α, a lack of or reduction in production of VEGF and MMP-9, which are key to angiogenesis, and therefore related to tumor progression." (PMID 28149530, 2017). "Baseline (b) MMP2 and MMP9 serum levels were independent from patient characteristics and circulating tumor or endothelial cells, and were not correlated to pCR." (PMID 26921265, 2016). "The presence of tumor cell-derived exosomes also clearly decreased the expression of established markers for osteoclast fusion and differentiation, including DC-STAMP, TRAP, cathepsin K, and MMP-9." (PMID 27832183, 2016). "At 25 days after injection of HepG2 cells that were transfected with siRNA-TM4SF1, tumor expression of MMP-2, MMP-9, and VEGF were significantly lower, but tumor expression of caspase-3, caspase-9, and TIMP were higher, relative to injection with control cells (p < 0.01 for all comparisons)." (PMID 27153056, 2016). "By suppressing myeloid-derived suppressor cell (MDSC) recruitment and MMP9, a matrix-degrading enzyme critical for pro-angiogenesis, HDL-C/ApoA-I may inhibit tumor angiogenesis, invasion and metastasis." (PMID 27344180, 2016). "TAN supports tumor growth by secreting VEGF and MMP9, which promote angiogenesis." (PMID 27259252, 2016). "Interestingly, increased expression of MMP-9 was also observed in the C666-1 cells at 24 hrs after co-culture and its expression continuously increased at 48 hrs, which suggests that these factors may be expressed by both cell types upon interaction to promote tumor aggressiveness." (PMID 27487154, 2016). "Furthermore, Mmp2, Mmp9, and Mmp13 become upregulated in MMTV-PyMT tumors and are also involved in tumor growth and metastasis." (PMID 27542270, 2016). "However, MMP knock-out mice revealed MMP9 as a key regulator of angiogenesis in this system, while MMP2 rather contributed to tumor growth." (PMID 26979530, 2016). "Therefore, the aim of this study was to compare the expressions of mRNA for metalloproteinases (MMP-2 and MMP-9) and type IV collagen in two different histological types of BCC (nodular and infiltrative) and in normal tissues from the tumor interface." (PMID 27406386, 2016).
tumor (continued). "Although this cluster relationship was not correlated to the tumor clinical stages, previous studies showed the same phenotypic progress with the low level of MMP9 (20q13.12) activity in the potential of HN31 and HN4 invasion, but not for HN30 and HN12." (PMID 27501229, 2016). "Moreover, neutrophils were shown to stimulate tumor angiogenesis via secretion of vascular endothelial growth factor (VEGF) and matrix metallopeptidase 9 (MMP9)." (PMID 28066438, 2016). "MMP-9, the most important MMP in SCC tumor growth, is stimulated by MMP-26." (PMID 27271600, 2016). "HE-induced suppression of MMP-9 in our study was accompanied with inhibition of endothelial cell migration, invasion, and tube formation, which emphasizes the critical role of MMP-9 and HE in tumor treatment." (PMID 26823953, 2016). "Thus we noticed a tumor nuclear reactivity for all MMPs but with high intensity especially for MMP-3 and MMP-9, which were also expressed in the cytoplasm and within amyloid deposits." (PMID 27871286, 2016). "These suggest that DNP may increase MMP-9 and VEGF expression through regulation of CLU, remodeling extracellular matrix (ECM) and promoting tumor angiogenesis, participate in NPC metastasis." (PMID 26716898, 2016). "siRNA knockdown of MMP9 in OVCA433 significantly reduced OVCA433 proliferation in co-culture, suggesting that MMP-9 secreted by OVCA433 during co-culture feeds back to the THP-1 to release HB-EGF and drive tumor cell proliferation." (PMID 27888810, 2016). "In addition to enhancing tumor invasion and metastasis directly, MMP-7 exerts indirect effects through the activation of MMP-2 and MMP-9." (PMID 27271600, 2016). "Additionally, we show that miR-204 acts as a tumor suppressor by regulating Rab40b and Tks5 expression and consequently inhibiting MMP2 and MMP9 targeting, which leads to a decrease in invadopodia-associated ECM degradation." (PMID 27789576, 2016). "However, both of the DOC/MMP-9 treated groups were effective in tumor regression, and more obvious inhibition effect on HNE-1 tumor was found when treated with FA-CD-PLLD/DOC/MMP-9." (PMID 27259274, 2016). "When MMP9 was knocked down in OVCA433, extended co-culture was unable to induce the expected increase in proliferation, indicating that the induction of MMP9 in the tumor cells was critical." (PMID 27888810, 2016). "The effects of HOXA11-AS on tumor progression may be mediated by genes involved in cell migration, invasion, and EMT-related genes; these genes include VEGF, MMP-9, MMP-2, E-cadherin, β-catenin, Vimentin, and Snail." (PMID 27792998, 2016). "Although MMP9 induction is controlled by various stimuli and signaling pathways, we have shown that PTK7 expression is positively correlated with MMP-9 expression in samples of ESCC tumor tissue from 155 patients." (PMID 27689325, 2016). "Some other studies also revealed that up-regulation of MMP-9 expression enhanced the chemotherapeutic resistance, and SSTR2 could suppress tumor growth and metastasis by inhibition of MMP-2 and -9 expressions indirectly." (PMID 27825139, 2016). "The invasion of tumor cells could be regulated by many factors such as BRMS1, E-cadherin, Keratin19, LOXL2, MMP9, Orai1, Stim1, TGF-β and VEGF." (PMID 27008697, 2016). "MMP-9 belongs to the zinc metalloproteinase family of proteins, which are involved in the remodeling and degradation of the ECM and thus facilitate the migration of tumor cells." (PMID 27893664, 2016). "MMP-9 is a type IV collagenase, and its high expression is closely correlated with malignant tumor invasion, metastasis and vascular formation via ECM and basement membrane degradation and damage near the tumor surface." (PMID 27187454, 2016). "The mechanism of radiation-induced knockdown of LGMN suppressing cell migration and invasion was next investigated with a focus on MMP9 and MMP2, a kind of gelatinase has the unique ability to degrade extracellular matrix components and facilitate tumor migration and invasion." (PMID 27656894, 2016).
tumor (continued). "In addition, fibroblast- or tumor cell-conditioned media upregulated the secretion of MMP-2 and MMP-9 in HNSCC cells." (PMID 26851944, 2016). "Moreover, MMP-10 up-regulates several other MMPs such as MMP-1, MMP-7, MMP-9, and MMP-13 that are essential for tumor progression." (PMID 27271600, 2016). "Despite the established pro‐tumorigenic roles of certain MMPs (e.g., MMP2, MMP9, and MT1‐MMP), recent studies have demonstrated that some MMPs such as MMP8 and MMP11 might act against tumor growth and metastasis." (PMID 27292876, 2016). "Multivariate analysis demonstrated that tumor MMP-9 expression was not an independent prognostic factor of recurrence (p = 0.142) or survival (p = 0.807)." (PMID 25888323, 2015). "This cleavage event can be found only in conditioned media and not in the serum of tumor-bearing mice, suggesting that the cleavage occurred as a result of action by MMP-9 resident in the tumor microenvironment, rather than enzymes circulating in blood." (PMID 25788424, 2015). "Moreover, OCT4B enhanced angiogenesis by the upregulation of CD34, VEGF, HIF-1α and IL-6, and promoted tumor cell mobility to the surrounding tissue by the upregulation of MMP2 and MMP9, and the induction of epithelial-mesenchymal transition (EMT)." (PMID 25816351, 2015). "The latent precursor of MMP9 was identified in all tumor types but not normal brain, whereas the active isoform was only observed in ACP." (PMID 25990246, 2015). "MMP-2, MMP-9, LOX, CXCR4, FN and p-FAK are involved in remodeling the tumor metastatic microenvironment, and whether miR-33b can regulate the metastatic microenvironment deserves further investigation." (PMID 25919570, 2015). "Immunohistochemical staining of tumor xenograft sections showed higher MMP-9 expression levels in the metastatic versus non-metastatic xenograft models." (PMID 28721370, 2015). "Therefore, we focused on MMP9 and MMP2 expression because they are the enzymes responsible for tumor invasion." (PMID 25774514, 2015). "We did not detect MMP-9 (using anti-human MMP-9 antibody) or register any significant change (using anti-mouse MMP-9) in the serum of tumor-bearing mice." (PMID 25788424, 2015). "MMP9 in particular is known to play a role in both tumor invasion through matrix degradation as well as angiogenesis, and VEGF plays a crucial role in the induction of new blood vessel formation in angiogenesis promoting tumor growth and survival." (PMID 26264026, 2015). "In addition to MMP2 and MMP9, we investigated the expression of MMP3, MMP11, MMP13 and MMP14 in tumour cells." (PMID 26284589, 2015). "Interestingly, CD151 can promote MMP-9 expression in some tumor cells, and RNAi-mediated suppression of CD151 in epidermal carcinoma cells led to the internalization of α3β1 accompanied by down-regulation of MMP-9." (PMID 25751421, 2015). "We reported in previous study that cyclin D1 and MMP-9 expression were decreased, and caspase 3 expression was increased by overexpression of SASH1 in U251 cells, supporting the role of SASH1 as a candidate tumor suppressor." (PMID 26424902, 2015). "In conclusion, considering markers from PA and MMP protease families that is critical in regulating tumor progression, our study reveals the greatest prognostic significance of PAI-2 among uPA, uPAR, PAI-1 and PAI-2 in the PA family and MMP-2 and MMP-9 in the MMP family." (PMID 26230665, 2015). "The results of the Cox regression analysis showed that tumor MMP-9 expression was not an independent prognostic indicator for DFS or OS." (PMID 25888323, 2015). "These tumor suppressive functions were paralleled at the molecular level by concomitant down-regulation of self-renewal (Bmi-1and Oct4A) and invasion related (MMP1 and MMP9) molecules in vitro." (PMID 26353754, 2015). "Patients with tumor MMP-9 expression had a shorter DFS than those without tumor MMP-9 expression (p = 0.01)." (PMID 25888323, 2015).